TMEM208 (transmembrane protein 208)
Description:
May function as a negative regulator of endoplasmic reticulum-stress induced autophagy.
Synonyms: HSPC171; hSND2; SND2
Tractability: Antibody: UniProt predicts a signal peptide or a membrane-spanning region.
Gene: Protein-coding gene on chromosome 16 (67,227,103 to 67,229,278, forward strand). Ensembl gene ENSG00000168701.
Subcellular location: Endoplasmic reticulum membrane
Gene Ontology:
Molecular function: protein binding
Biological process: vacuolar protein processing
Cellular component: endoplasmic reticulum membrane; vacuole
Genetic constraint (gnomAD): Loss-of-function variants: 19 observed, 27.31 expected, observed/expected ratio (o/e) 0.7, 90% interval 0.48 to 1.02. The upper end of that interval is the gene's LOEUF score, 1.02, which puts it in group 4 of 6, group 1 being the genes least tolerant of losing a copy. Missense variants: 183 observed, 222.61 expected, observed/expected ratio (o/e) 0.82, 90% interval 0.73 to 0.93. Synonymous variants: 93 observed, 85.1 expected, observed/expected ratio (o/e) 1.09, 90% interval 0.92 to 1.3.
Homologues: Orthologues: macaque TMEM208 (99% identical), dog TMEM208 (99% identical), guinea pig TMEM208 (98% identical), rabbit TMEM208 (98% identical), chimpanzee TMEM208 (97% identical), mouse Tmem208 (96% identical), rat Tmem208 (92% identical), tropical clawed frog tmem208 (75% identical), zebrafish tmem208 (72% identical), Drosophila melanogaster CG8320 (43% identical), Caenorhabditis elegans tmem-208 (32% identical).
Diseases named in the same sentence as TMEM208 in open-access papers:
TMEM208 is named in the same sentence as 4 diseases in open-access papers, as found by Europe PMC text mining. Sharing a sentence is not in itself a finding about the gene and the disease. The quoted sentences say what the papers report.
colon cancer (1 paper, 2017). "Our results show that there are two genes, namely TMEM208 and PQLC2, which remain transcriptionally stable in colon cancer treated with aspirin." (PMID 28184026, 2017). "Furthermore, we detected whether different concentrations of aspirin treatment caused the expression change in TMEM208 and PQLC2, and the result showed that the expression of both genes was stable in colon cancer cells treated with different concentrations of aspirin." (PMID 28184026, 2017). "Taken together, we identified that TMEM208 and PQLC2 are the optimized internal reference genes in colon cancer cells treated with aspirin." (PMID 28184026, 2017). "After aspirin treatment for one month, the tumor weight was significantly decreased in a dose dependent manner, whereas the ratio of TMEM208 to PQLC2 was not altered in the xenografts of colon cancer after aspirin treatment." (PMID 28184026, 2017). "To detect if TMEM208 and PQLC2 could be widely used as the ideal internal reference genes in colon cancer cells treated with aspirin, we additionally tested them in SW480 and SW1116 cells." (PMID 28184026, 2017). "Finally, we evaluated that if TMEM208 and PQLC2 are ideal to serve as internal references for colon cancer treated with aspirin in vivo." (PMID 28184026, 2017). "Moreover, we detected that if aspirin treatment affected the mRNA decay of TMEM208 and PQLC2 in colon cancer cells." (PMID 28184026, 2017).
colorectal cancer (1 paper, 2017). A primary or metastatic malignant neoplasm that affects the colon or rectum. "Thus TMEM208 and PQLC2 are the appropriate reference genes for gene transcription analysis in colorectal cancer cells following aspirin treatment." (PMID 28184026, 2017).
tumor (4 papers, 2013 to 2023). "Additionally, numerous studies have shown that TMEM123 and TMEM66 in T cells, and TMEM208, TMEM59, and TMEM258 in B cells, are closely related to inflammatory response and participate in tumor immune response, which is consistent with our findings." (PMID 37265785, 2023).
infection (1 paper, 2023). The state of being infected such as from the introduction of a foreign agent such as serum, vaccine, antigenic substance or organism. "Moreover, the control/NMD-sensitive transcript ratio for TMEM208 at 9 h post-infection was also significantly higher in infected versus non-infected cells." (PMID 36768954, 2023). "We found that the control (protein-producing)/NMD-sensitive transcript ratio was overall stable over time for both genes in non-infected cells, while it increased in favor of the control isoform (not targeted by NMD) at 3 and 9 h after infection for RPL12 and TMEM208, respectively." (PMID 36768954, 2023).